BCL2 (BCL2 apoptosis regulator)
Diseases named in the same sentence as BCL2 in open-access papers (continued):
Sharing a sentence is not in itself a finding about the gene and the disease.
squamous cell carcinoma (40 papers, 2000 to 2025). A carcinoma arising from squamous epithelial cells. "In the same study, although the clinicopathologic features of tuft-like NEC and tuft-like squamous cell carcinoma (SQ) were different, both tumor types co-expressed BCL2 and KIT." (PMID 40406790, 2025). "In OSCC, the correlation between histopathological grading of OSCC and Bcl-2 expression showed higher Bcl-2 expression in poorly differentiated squamous cell carcinoma as compared to well-differentiated and moderately differentiated squamous cell carcinoma." (PMID 39252711, 2024). "In the second approach, apoptosis-sensitive human epidermoid carcinoma (A431) cells were transfected with a eukaryotic expression vector (pSFFV/neo) containing an EcoRI fragment of human Bcl-2 cDNA, resulting in Bcl-2 overexpression." (PMID 39596137, 2024). "Bcl-2 expression evaluation was done for each case of oral epithelial dysplasia and squamous cell carcinoma." (PMID 39252711, 2024). "Fifty-one percent of squamous cell carcinomas (SCCs) and 34.8% of adenocarcinomas (ACs) expressed Bcl-2." (PMID 36766867, 2023). "There are variable and inconsistent reports in literature regarding expression of bcl-2 in squamous cell carcinoma of oropharynx by various authors." (PMID 34178320, 2021). "Present study was conducted with the aim to study the bcl-2 expression in squamous cell carcinoma of oropharynx and to correlate expression of bcl-2 with tumor grade." (PMID 34178320, 2021). "Meanwhile, in squamous cell carcinoma tissue, Bcl-2 expression was higher, while the Caspase-3, Caspase-9 and Bax were significantly decreased." (PMID 31666604, 2019). "The results obtained here agreed with other reports that hydrophobic fractions extracted from many species are able to change the expression levels of Bcl-2 and Bax genes in KB human oral epidermoid carcinoma cells." (PMID 30190788, 2018). "In the training cohort, Bcl-2 expression was identified in 90 (50%) of NSCLCs, including 51 (46%) adenocarcinomas (AC), 23 (62%) squamous cell carcinomas (SCC), 5 (45%) large cell carcinomas (LCC) and 6 (46%) adenosquamous carcinomas (AS)." (PMID 20459695, 2010). "Interestingly, while Bcl-2 proteins can regulate ROS production, that is a two-way street in which ROS increases have been shown to reduce the expression of Bcl-2, and both Bcl-2 and Bcl-xL phosphorylation in squamous cell carcinoma cells." (PMID 39857806, 2025). "Hence, the present study evaluated the expression of the Bcl-2 marker in the oral cavity's dysplastic lesions and squamous cell carcinoma." (PMID 39252711, 2024). "Inhibition of Cx43 expression using siRNA increased Bcl-2 protein levels in SCC25 (tongue squamous cell carcinoma) cells, while forced Cx43 expression reduced Bcl-2 levels and supported paclitaxel cytotoxicity in FaDu (hypopharynx squamous cell carcinoma) cells." (PMID 31766723, 2019). "Moreover, in squamous carcinoma both the over expression of Bcl-2 or EGFR activation induced EMT, promoting cell migration and invasion via the ERK1/2 and PI3K-regulated MMP-9/E-cadherin signaling pathways." (PMID 25277187, 2014). "Both FBXW7 and Bcl-2 inhibition were predictive for efficacy of SAHA in squamous cell carcinoma." (PMID 25568669, 2014). "In the NSCLC group, 32% of the squamous cell cancer and 61% of the adenocarcinoma expressed Bcl-2." (PMID 12838300, 2003).
squamous cell carcinoma (continued). "We found a sustained increase in Bcl-2, Beclin-1, ATG5,LC-3 and p-AktSer473 associated with decreased expression of Bax and cleaved caspase-3 during progression of normal epithelium through hyperplasia, dysplasia and well-differentiated squamous cell carcinoma of the hamster buccal pouch." (PMID 30352996, 2018). "In squamous cell carcinoma cells, knockdown of GADD45A inhibits apoptosis, with the reduction of BAX gene expression and induction of BCL-2 gene expression." (PMID 33406670, 2021). "Results indicated that c-Myc, c-Jun, Bcl-2, hypoxia inducible factor-1α (HIF-1α), vascular endothelial growth factor (VEGF), matrix metalloproteinase-9 (MMP-9), ERK 1/2 and pERK1/2 were overexpressed in a cellular model of squamous cell carcinoma, Cal-27." (PMID 35890188, 2022). "Similarly, Bcl-2 overexpression has been reported to induce partial EMT and promote squamous carcinoma cell invasion and metastasis." (PMID 23826359, 2013). "We demonstrated a survival benefit for Bcl-2 expression in patients with non squamous histology absent in squamous cell carcinomas and this observation confirms the effect of histology for prognostic stratification of NSCLC patients." (PMID 20459695, 2010). "In the case of squamous cell carcinoma, E-cadherin-mediated cell-cell adhesion was found to induce epidermal growth factor receptor (EGFR) activation, which triggers the ERK/MAPK signaling module and further blocks down-regulation of the anti-apoptotic protein Bcl-2, promoting tumor cell survival." (PMID 24797520, 2014). "However, according to previous studies, the role of Cyclin D1 as a prognostic marker remains controversial and there is no consensus on the use of Bcl-2 as a prognostic marker for squamous cell carcinomas among head and neck cancer patients either." (PMID 23451060, 2013). "Interestingly no survival benefit was found for the high expressing Bcl-2 squamous cell carcinomas (median survival 26 vs. 21 months for the high and low expressers respectively; log rank p = 0.3; data not shown)." (PMID 20459695, 2010).
heart failure (39 papers, 2013 to 2026). Inability of the heart to pump blood at an adequate rate to meet tissue metabolic requirements. "The expression levels of Bcl-2, Cyto-c and caspase-3 genes, which are associated with the severity of heart failure and apoptosis in myocardial cells, were also examined with RT-PCR." (PMID 25898913, 2015). "In the heart, Bcl2 is involved in myocyte cell loss and contributes to a variety of cardiac pathologies, including heart failure and IR injury." (PMID 26299920, 2015). "Bcl-2 as an anti-apoptotic protein plays an important role in maintaining the mitochondrial structure and function and inhibiting cell apoptosis is a potent downward regulation of Bcl-2 causing heart failure." (PMID 33374365, 2020). "Indeed, BCL2 is involved in myocyte cell loss that contributes to a variety of cardiac pathologies, including heart failure." (PMID 28666417, 2017). "In conclusion, NAC may inhibit oxidative stress, suppress NF-κB activation and regulate the expression of apoptosis-associated genes, such as Bax and Bcl-2, which may in turn reduce myocardial cell apoptosis and inflammation, and improve cardiac function in heart failure." (PMID 24889421, 2014). "The treatment also regulated apoptosis-related protein expression, partially reversing the increase in cleaved Caspase-9, cleaved Caspase-3, and Bax and the suppression of Bcl-2 observed in the heart failure rats." (PMID 39605071, 2024). "For instance, SPRC was reported to attenuate cell apoptosis in a heart failure rat model by inhibiting caspase activation and increasing the ratio of Bcl-2/Bax." (PMID 38328305, 2023). "In cluster 1, it is intriguing to note the presence of a total of 44 different items in Cluster 1, including apoptosis, cell-death, heart-failure, hypertrophy, remodeling, bax, bcl-2, caspase-3, ischemia, reperfusion, ventricular myocytes, and others." (PMID 37746983, 2023). "PPARγ activation prevents cardiac insufficiency by inhibiting apoptosis and necrosis, and by regulating PPARγ expression, it induces Bcl-2, Bax, and cytochrome-c expression changes and attenuates cardiomyocyte apoptosis." (PMID 36420656, 2022). "The increase in Bcl-2 plays an important role in the development of heart failure and chronic liver disease." (PMID 34604209, 2021). "We also observed that antagomir‐208a overexpression enhanced Bcl‐2 expression in a model of heart failure induced by volume overload." (PMID 33605072, 2021). "The prosurvival factors Bcl-xL and Bcl-2 have been observed in patients with end-stage heart failure and in cultured cardiomyocytes upon exposure to cytotoxic cytokines." (PMID 32426037, 2020). "Tumor necrosis factor α (TNF-α) and the apoptotic signaling molecule BCL2 play important roles in the progression of heart failure." (PMID 33273955, 2020). "Our selected candidates included many therapeutic targets for heart failure including Atp2a2, Bcl2, Sod2 and Sirt323,24,28,41." (PMID 31705051, 2019). "By increasing BCL2 expression, miR-21 promotes heart failure progression with preserved left ventricular ejection fraction and subsequently inhibits cardiac fibrosis." (PMID 29348768, 2017). "On molecular level, myocardial ANKRD1 and serum adiponectin correlated with low BAX/BCL-2 ratios, indicative of antiapoptotic tissue propensity observed during the worsening of heart failure." (PMID 25961010, 2015). "Thus, the electron transport chain driven decrease in bcl-2 content not only affects the acute injury during early reperfusion but also likely contributes to continued cardiomyocyte loss as reperfusion continues, predisposing toward heart failure during later periods of attempted recovery." (PMID 25756500, 2015). "It has been demonstrated that matrine exerts protective effects against heart failure by decreasing the expression of caspase-3 and Bax, and increasing Bcl-2 levels." (PMID 26135032, 2015).
heart failure (continued). "Astragalus also reduced expression of BAX in heart failure rats and increase Bcl-2 expression by Astragaloside IV, a main component in Astragalus." (PMID 25342960, 2014). "Our results further demonstrated that combined metoprolol and terbutaline prevented the changes in both Bcl-2 and Bax proteins in MI-induced heart failure." (PMID 25187901, 2014). "Therefore, the present study aimed to investigate the molecular mechanism of regulating miR‐499 and miR‐208a on Bcl‐2 protein expression in stretched atrial fibroblasts and in a rat model of volume overload‐induced heart failure." (PMID 33605072, 2021). "Our previous animal experiments showed that FXHJ could effectively reduce the level of TNF-α in rats with heart failure, improve the expression of the BCL2 gene, and thus inhibit a variety of myocardial cell apoptosis pathways." (PMID 33273955, 2020). "In studies carried out in cardiac myocytes of patients with heart failure, the expression of the protein from the Bax protein was increased, while the Bcl-2 expression was decreased, resulting in a decrease in the Bax/Bcl-2 ratio, indicating that cell apoptosis was increased in cardiac myocytes." (PMID 33145109, 2020). "Furthermore, it has been reported that Mat exerts protective effects against heart failure by inhibiting the upregulation of Bax, caspase-3 and increasing the expression of Bcl-2 in rats." (PMID 26135032, 2015). "However, the study by Tong’s group reported that miR-21 promoted cardiac fibrosis and development of heart failure with preserved left ventricular ejection fraction by up-regulating BCL-2." (PMID 26132560, 2015). "In addition, molecular signature may be possible as recently proposed for in situ expression of Bcl-2 in PAECs from patients with pulmonary hypertension relative to heart failure with preserved ejection fraction." (PMID 34831453, 2021). "In rats with ADR-induced heart failure, ADR induces an increase in the expression of proapoptotic cytokines, which is shown by the significant increase in the ratio of Bax/BCL-2." (PMID 34108879, 2021). "As part of the mechanism induced to prevent heart failure and ischemia/reperfusion damage, BAG3 promotes cell survival through binding to several proteins including hsp70 and Bcl2." (PMID 30792263, 2019). "Studies have shown that airborne polystyrene nanoplastic exposure leads to heart failure through ECM–receptor interactions and the PI3K/AKT/BCL-2 pathway; another study indicates that PS microplastics accumulate in the intestines, causing enteritis and posing serious health risks." (PMID 41463487, 2025). "To further investigate the therapeutic targets for heart failure, we performed sensitivity analyses (local sensitivity analysis (LSA) and global sensitivity analysis (GSA)) of the network model by examining the influence of parameter perturbations on Bcl-2 expression." (PMID 25517116, 2014).
chronic myeloid leukemia (36 papers, 2007 to 2025). "Major advances were made in the treatment of chronic myeloid leukaemias and gastrointestinal tumours by using drugs that directly inhibit the pathways deregulated by the BCL2-ABL fusion gene and c-KIT mutations." (PMID 17406368, 2007). "Moreover, the latest papers demonstrated the inhibition of c-Myc and Bcl-2 caused by icaritin in both acute and chronic myeloid leukemia." (PMID 24895574, 2014). "The response to imatinib in chronic myeloid leukemia can be regulated by CCN1 through the NF-κB/Bcl-2 pathway." (PMID 40234387, 2025). "In order to explore the mechanism of Caulis Spatholobi in the treatment of chronic myeloid leukemia, we selected Bcl-2, Bax, caspase-3, and other classical proteins that play an important role in cell apoptosis for further experimental verification." (PMID 37073142, 2024). "In the chronic myeloid leukemia K562 cell line, stellettin B increased the expression levels of Bad and Bax and decreased Bcl-2 levels." (PMID 35955957, 2022). "The EO from the leaves of Pinus roxburghii induced apoptosis along with inhibition of NF-κB and inhibited the expression of genes associated to cell survival (survivin, c-FLIP, Bcl-2, Bcl-xL, c-Myc, c-IAP2), proliferation (cyclin D1), and metastasis (MMP-9) in KBM-5 (chronic myeloid leukemia) cells." (PMID 30441836, 2018). "Interestingly, the immunosensor was applied to investigate Bcl-2 and Bax expressions from nilotinib-treated chronic myeloid leukemia K562 cells, and to evaluate the drug effect through the Bax/Bcl-2 ratio." (PMID 28448466, 2017). "WGS promises to offer a new level of personalized therapy, as illustrated here and in other cases such as the recent use of WGS to identify BCL2 inhibitors as a therapeutic option for a patient with chronic myeloid leukemia (CML) resistant to ponatinib therapy." (PMID 28487881, 2017). "Additionally, a recent study reported that P15INK4B down-regulated Bcl-2 expression in chronic myeloid leukemia cells." (PMID 27095571, 2016). "It has been recently reported that one of the Nox isoforms, Nox4, is expressed in the mitochondria in the rat renal cortex, cardiac myocytes, and in the mitochondria-enriched heavy membrane fractions of the chronic myeloid leukemia cells that overexpress the antiapoptotic protein Bcl-2 (CEM/Bcl-2)." (PMID 22593827, 2012). "In summary, curcumin treatment might produce a P73-dependent apoptotic cell death in chronic myelogenous leukemia cells (K562), which was triggered by mitotic catastrophe, due to sustained BAX and survivin expression and impairment of the anti-apoptotic proteins BCL-2 and XIAP." (PMID 27832139, 2016).
depression (36 papers, 2012 to 2026). "An associative analysis with known disease databases identified BCL2 as the most significant hub gene, associated with a variety of diseases, such as bipolar disorder, memory disorder, learning disorder, AD, and major depressive disorder." (PMID 40520536, 2025). "Among targets that have been experimentally validated and that are co-expressed in prefrontal cortex, at least three (VEGFA, BCL2, and DNA methyltransferase 3B) have been previously implicated in depression or suicide." (PMID 22427989, 2012). "We also observed the mRNA expression levels of two apoptosis-associated genes (Bax and Bcl-2) to explore whether CUMS-induced depression caused liver injury." (PMID 27006086, 2016). "SSA therapy significantly enhanced the expression of p-CREB and BDNF, decreased the expression of Bax and Caspase-3, elevated the expression of Bcl-2, and inhibited the death of hippocampal neurons, thereby ameliorating depression-like behavior in PSD rats." (PMID 40458804, 2025). "SSA therapy markedly enhanced the expression of p-CREB and BDNF, decreased the expression of Bax and Caspase-3, elevated the expression of Bcl-2, and inhibited the death of hippocampal neurons, therefore ameliorating depression-like behavior in PSD rats." (PMID 40458804, 2025). "SCFAs supplementation optimized METH-induced microbial dysbiosis, ameliorated colonic inflammation, and repressed anxiety- and depression-like behaviors.Protecting neurons from gp120 invasion by regulating the expression of bcl-2." (PMID 39224601, 2024). "Icariin exerts inhibitory effects on hippocampal apoptosis in the CUMS-induced depression rat model by downregulating the expression levels of Bax, caspase-3, cleaved caspase-3, and cytochrome C and upregulating the expression of Bcl-2." (PMID 38915473, 2024). "In an experimental study, ursolic acid prevented chronic unpredictable stress-induced depression-like behavior via modulating Bcl-2/Bax gene expression." (PMID 38505421, 2024). "Patients with depressive disorders are characterized by low expression of the anti-apoptotic Bcl-2, but treatment with antidepressants increased Bcl-2 levels." (PMID 34769286, 2021). "These pathways are linked to the core genes chiefly including FOS, IL6, TNF-α, Bcl-2, c-Jun, ERK, and EGF gene in our research in the treatment of depression." (PMID 32997725, 2020). "Molecular docking showed that telocinobufagin and beta-sitosterol, the active ingredients of Shan-Zhu-Yu, can act on NR3C1, Bax, and Bcl-2 to treat depression." (PMID 33299459, 2020). "Studies on post-mortem FC tissues from patients with bipolar disorder show that Bcl-2 is downregulated in depression, and also a rat study suggests that in chronic mild stress, VLX reverses the activated pro-apoptotic pathways." (PMID 25423262, 2014). "There was a significantly higher ratio of Bax:Bcl-2 (mean ± SEM) in the myocardium in the depression, MI and post-MI depression groups than in the sham group (P < 0.01)." (PMID 23394076, 2013). "Wann has shown behavioral changes and an increased Bax/Bcl-2 protein ratio in limbic areas in rats with post-MI depression, suggesting a role of apoptotic events, which is similar to human findings." (PMID 23394076, 2013). "The ratio of Bax-Bcl-2 was significantly larger in MI group than the depression group (P < 0.05), and this ratio was significantly greater in the post-MI depression group compared with the MI group (P < 0.05)." (PMID 23394076, 2013). "We measured protein levels of several selected target proteins implicated in depression (DMNT3b, VEGFA, and BCL2) in all individuals by Western blotting (normalizing values using beta-acting immunoreactivity)." (PMID 22427989, 2012). "In summary, we speculated that CYWD may inhibit neuronal apoptosis by activating the AKT/CREB pathway and regulating proteins such as Bcl-2, Bax, and Caspase 3, so as to protect hippocampal neurons and play a role in the treatment of depression." (PMID 41221044, 2025).